ZSWIM2 (zinc finger SWIM-type containing 2)
Description:
E3 ubiquitin-protein ligase involved in the regulation of Fas-, DR3- and DR4-mediated apoptosis. Functions in conjunction with the UBE2D1, UBE2D3 and UBE2E1 E2 ubiquitin-conjugating enzymes.
Synonyms: MEX; ZZZ2; MGC33890
Tractability: PROTAC: UniProt records ubiquitination sites on it.
Gene: Protein-coding gene on chromosome 2 (186,827,475 to 186,849,208, reverse strand). Ensembl gene ENSG00000163012.
Gene Ontology:
Molecular function: ubiquitin protein ligase activity; ubiquitin-protein transferase activity; zinc ion binding
Biological process: protein polyubiquitination
Genetic constraint (gnomAD): Loss-of-function variants: 27 observed, 35.26 expected, observed/expected ratio (o/e) 0.77, 90% interval 0.56 to 1.06. The upper end of that interval is the gene's LOEUF score, 1.06, which puts it in group 4 of 6, group 1 being the genes least tolerant of losing a copy. Missense variants: 686 observed, 661.79 expected, observed/expected ratio (o/e) 1.04, 90% interval 0.97 to 1.1. Synonymous variants: 205 observed, 233.12 expected, observed/expected ratio (o/e) 0.88, 90% interval 0.78 to 0.99.
Homologues: Orthologues: chimpanzee ZSWIM2 (99% identical), macaque ZSWIM2 (95% identical), pig ZSWIM2 (79% identical), rabbit ZSWIM2 (73% identical), dog ZSWIM2 (72% identical), guinea pig ZSWIM2 (71% identical), rat Zswim2 (70% identical), mouse Zswim2 (68% identical), zebrafish zswim2 (33% identical).
Diseases named in the same sentence as ZSWIM2 in open-access papers:
ZSWIM2 is named in the same sentence as 2 diseases in open-access papers, as found by Europe PMC text mining. Sharing a sentence is not in itself a finding about the gene and the disease.
ZSWIM2 shares sentences with these, for which no sentence is quoted: breast carcinoma (1 paper); viral infection (1).